ZNF737 (zinc finger protein 737)
Description:
May be involved in transcriptional regulation.
Synonyms: ZNF102
Tractability: PROTAC: ubiquitination databases record sites on it.
Gene: Protein-coding gene on chromosome 19 (20,535,825 to 20,565,809, reverse strand). Ensembl gene ENSG00000237440.
Subcellular location: Nucleus
Pathways (Reactome):
Gene expression (Transcription): Generic Transcription Pathway
Gene Ontology:
Molecular function: DNA-binding transcription factor activity, RNA polymerase II-specific; RNA polymerase II cis-regulatory region sequence-specific DNA binding
Biological process: regulation of DNA-templated transcription; negative regulation of transcription by RNA polymerase II
Cellular component: nucleus
Genetic constraint (gnomAD): Loss-of-function variants: 12 observed, 11.1 expected, observed/expected ratio (o/e) 1.08, 90% interval 0.69 to 1.7. The upper end of that interval is the gene's LOEUF score, 1.7, which puts it in group 6 of 6, group 1 being the genes least tolerant of losing a copy. Missense variants: 633 observed, 626.59 expected, observed/expected ratio (o/e) 1.01, 90% interval 0.95 to 1.08. Synonymous variants: 217 observed, 210.92 expected, observed/expected ratio (o/e) 1.03, 90% interval 0.92 to 1.15.
Homologues: Paralogues in human: ZNF66 (80% identical), ZNF626 (75% identical), ZNF92 (75% identical), ZNF675 (72% identical), ZNF98 (70% identical), ZNF257 (70% identical), ZNF430 (70% identical), ZNF723 (69% identical), ZNF431 (69% identical), ZNF253 (69% identical), ZNF680 (68% identical), ZNF273 (68% identical), and 6 more.
Diseases named in the same sentence as ZNF737 in open-access papers:
ZNF737 is named in the same sentence as 3 diseases in open-access papers, as found by Europe PMC text mining. Sharing a sentence is not in itself a finding about the gene and the disease. The quoted sentences say what the papers report.
bladder cancer (1 paper, 2025). "We also found an inverse association between whole blood expression of ZNF737 and bladder cancer risk." (PMID 39789109, 2025). "A total of four genes (SLC39A3 on 19p13.3, ZNF737 on 19p12, FAM53A on 4p16.3, and PPP1R2 on 3q29) were identified to be associated with bladder cancer risk with FDR < 0.05." (PMID 39789109, 2025). "Higher whole blood expression of FAM53A and PPP1R2 was associated with higher odds of bladder cancer, while higher expression of SLC39A3 and ZNF737 was associated with lower odds of bladder cancer." (PMID 39789109, 2025). "TWAS identified four genes for which expression levels were associated with bladder cancer risk: SLC39A3 (OR = 0.91, CI = 0.87–0.95, FDR = 0.015), ZNF737 (OR = 0.91, CI = 0.88–0.95, FDR = 0.016), FAM53A (OR = 1.09, CI = 1.05–1.14, FDR = 0.022), and PPP1R2 (OR = 1.09, CI = 1.05–1.13, FDR = 0.049)." (PMID 39789109, 2025). "We did not identify any GWAS-identified bladder cancer risk SNPs located within 1 Mb of SLC39A3, ZNF737, and PPP1R2." (PMID 39789109, 2025).
cancer (1 paper, 2019). A tumor composed of atypical neoplastic, often pleomorphic cells that invade other tissues. "The FN1 and ZNF737 genes are relatively well-known cancer-related genes." (PMID 30911020, 2019).
ZNF737 also shares sentences with these, for which no sentence is quoted: tumor (1 paper).